IL10 (interleukin 10)
Diseases named in the same sentence as IL10 in open-access papers (continued):
Sharing a sentence is not in itself a finding about the gene and the disease.
Sepsis (continued). "IL-10 appears to play a pivotal role in controlling the magnitude of inflammatory responses during either systemic or pulmonary inflammation, and has been proposed as a key mediator of beneficial effects in CLP-induced experimental sepsis." (PMID 24406030, 2013). "IL-10 impairs MHC class II recycling leading to decreased surface expression of HLA-DR, and a negative correlation of IL-10 and monocyte HLA-DR expression has been observed in patients with sepsis." (PMID 23446058, 2013). "Therefore, IL-10 and sCD25 should be considered not only as late but also as early mediators of bacteremic SIRS and sepsis." (PMID 23561467, 2013). "However, in a mouse model of sepsis, analyzing spleen NK cells, we recently showed that TGF-β, more than IL-10, was the deactivating cytokine." (PMID 23098236, 2012). "In this work, the capacity to produce IL-12 and TNF-α from PBMCs of patients with severe sepsis was diminished, whereas the release of IL-10 was not affected." (PMID 21939530, 2011). "Alleles -7202G and 248Ser, and the 248Ser-602Ile haplotype were associated with circulatory dysfunction among severe septic patients (0.001≤p≤0.022), and with reduced IL-10 (0.012≤p≤0.047) and elevated CRP (0.011≤p≤0.036) serum levels during the first week of sepsis development." (PMID 21048935, 2010). "Given the relevance of IL-10 in sepsis, the effect of CB2 receptor activation on IL-10 release is likely to be a major determinant of the immunomodulatory action of CB2 receptor activation in sepsis." (PMID 19641602, 2009). "Similar results have been found in the subgroups of septic and non-septic patients, except for the correlation with IL-10, which showed no statistical significance in the group of non-sepsis patients." (PMID 19545363, 2009). "Inflammatory status was assessed in sepsis patients by measuring TNF-α and IL-10, to elucidate whether it could account for differences observed in MMPs and TIMP-1." (PMID 19799791, 2009). "Sepsis starts as a process of intravascular inflammation mediated by pro-inflammatory cytokines/chemokines including TNF-α, MIP-1α, MCP-1, IFN-γ, and IL-17 as well as anti-inflammatory cytokines, e.g. IL-10." (PMID 18937852, 2008). "We compared cytokine concentrations among patients with severe sepsis and septic shock, and observed that concentrations of IL-1β, IL-6, IL-7, IL-8, IL-10, IL-13, IFN-α, MCP-1 and TNF-α were significantly increased in septic shock as compared with severe sepsis." (PMID 17448250, 2007). "This included traditionally evaluated cytokines (IL-1β, IL-6, IL-8, IL-10 and TNF-α) and a number of cytokines that are not commonly associated with sepsis (IL-7, IL-13, IFN-γ and MCP-1)." (PMID 17448250, 2007). "Variation in the IL-10, IL-6 and CD14 genes may be genetic factors influencing the development and outcome of sepsis in the premature newborn." (PMID 16611358, 2006). "No significant trend between haplotype and risk for sepsis was observed, although the highest incidence of late BSI was in infants with the IL-10 -1082AA: IL-6 -174 CC haplotype." (PMID 16611358, 2006). "Together, these data indicate that some peritoneal cell types require triglyceride uptake to increase IL-10 production during sepsis in fluoxetine-pretreated mice, but ultimately the fluoxetine-mediated increase in circulating and hepatic IL-10 during sepsis is independent of triglyceride uptake." (PMID 39951524, 2025). "IL-10, while primarily anti-inflammatory, has shown value as a “rule-out” marker due to its high specificity and negative predictive value for bacteremia and sepsis." (PMID 40647525, 2025). "Notably, IL-10 potently inhibits CD4 Tcell activation and function, whilepromoting proliferation, survival and anti-inflammatory functions of regulatory Tcells in sepsis, which further augment immunosuppression duringsepsis." (PMID 40458301, 2025).
Sepsis (continued). "Conversely, the absence of significant differences in IL-10 levels between Sepsis_A and SIRS groups indicates that this cytokine may have limited diagnostic value in distinguishing early sepsis from non-infectious SIRS." (PMID 41301767, 2025). "For example, interleukin (IL)-1, IL-6, IL-12, interferon (IFN)-γ, macrophage migration inhibitory factor (MIF), IL-10, transforming growth factor (TGF)-β, and IL-4 attempt to restore the immunological equilibrium and balance the pro- and anti-inflammatory cascades during sepsis." (PMID 40142568, 2025). "Furthermore, fluoxetine pretreatment did not protect Il10−/− mice from sepsis-induced morbidity, and protection against mortality was reduced by more than 70%." (PMID 39951524, 2025). "Additionally, the blockade of APOH after CLP led to a significant increase in the levels of serum and peritoneal inflammatory cytokines, such as TNF-α, IL-1β, and IL-6, alongside a decrease in IL-10 levels after non-severe sepsis." (PMID 38291524, 2024). "Similarly, IL-10 serum levels were found to peak on the first day post-burn and decline thereafter, with greatest concentrations correlating to percent TBSA burned and the presence of sepsis." (PMID 39716257, 2024). "The decreased secretion of IL-12 by DCs contributes to activation incompetence, but rising IL-10 level dampens the differentiation of interferon-γ (IFN-γ)-producing T helper type 1 (Th1) cells and the activation of natural killer (NK) cells in CLP-induced sepsis." (PMID 39040114, 2024). "To investigate whether the anti-PD-L1 antibody affected monocyte function, we selected three important cytokines, IL-6, IL-10, and TNF-α, used ELISA to assess cytokine production in the CLP-induced sepsis model and anti-PD-L1 antibody-treated septic mice at 24, 48, and 72 h." (PMID 37776443, 2024). "Previous research in patients with systemic lupus and sepsis demonstrated that nonclassical monocytes have an inflammatory phenotype upon activation by high levels of proinflammatory cytokines and low levels of anti-inflammatory IL-10." (PMID 38398067, 2024). "The proportion of patients who developed sepsis was significantly (p < 0.01) higher in the high IL-10 and high NEWS (N = 53; 88.3%) as opposed to the low IL-10 and high NEWS (N = 11; 61.1%) subgroup, with similar results also found for combinations of high IL-10 and SIRS." (PMID 39212218, 2024). "Importantly, while PGE2 levels did not change after induction of sepsis in the different groups, IL-10 (up to 48 h) and TGF-ß levels (up to 7 days) increased significantly in the groups receiving ADSC treatment, especially those receiving a high dose." (PMID 38087374, 2023). "Although our study demonstrates the presence of IL-10-secreting B cells in patients with sepsis-induced ARDS and a higher percentage compared to other PBMC cells, the precise relationship between IL-10 levels in circulating PBMC and lung injury severity remains unclear." (PMID 37443161, 2023). "However, over-administration of the IL-10 contained in MSC secretome could play a role in immunosuppression in the later phases of sepsis, which correlates with increased sepsis severity and poor prognosis." (PMID 37626822, 2023). "Finally, to determine whether the EM enhanced by B cell–derived IL-10 contributes to host protection during infections, we induced CLP, the most frequently used model for human sepsis, in Il10ΔCd19 mice and their littermate control (Il10fl/fl) mice." (PMID 36719648, 2023). "Importantly, G-MDSCs, but not M-MDSCs, as well as IL-10 production, are required for full protection against lethal sepsis." (PMID 37681975, 2023). "To determine whether Erbin-mediated autophagy regulates sepsis-induced inflammatory response and organ injury, we investigated the level of inflammatory cytokines TNF-α, IL-6, IL-1β, HMGB1, and IL-10 in polymicrobial sepsis mice and MDP-treated BMDMs with CQ treatment." (PMID 38105228, 2023).
Sepsis (continued). "In our study, we found that injecting parenteral ω-3 PUFA solutions reduced IL-1β, TNF-α, IL-6, IL-10, IFN-γ, and IL-17 levels and hindered the secretion of multi-organ injury markers induced by CLP treatment, indicating the protective role of ω-3 PUFAs in sepsis." (PMID 36694426, 2023). "For example, in Listeria monocytogenes infection, the NK cell-derived IL-10 shows detrimental effects on host resistance against the invasive pathogen, whereas it can protect the host from murine cytomegalovirus infection or CLP-induced sepsis by reducing systemic inflammation." (PMID 36776839, 2023). "A meta-analysis of an animal model of sepsis with resveratrol intervention suggested that resveratrol can reduce the sepsis-induced inflammatory response by reducing TNF-α, MDA, and IL-6 levels; increasing IL-10 levels; and improving mean arterial pressure, thus improving the microcirculation." (PMID 35222035, 2022). "Moreover, in agreement with our findings, it was reported that patients with stress hyperglycemia during severe sepsis had higher serum levels of IL-10 and worse clinical outcomes when compared to those with normoglycemia or pre-existing diabetes." (PMID 36059840, 2022). "Interestingly, sepsis also evoked a robust increase in plasma level of the anti-inflammatory cytokine IL-10, whose systemic concentration was not significantly affected by PF271 treatment." (PMID 35178052, 2022). "Additionally, LR12 treatment protected mice from sepsis-induced vascular dysfunction, measured by improved vascular contractility, and attenuated IL-6, TNF-α, and IL-10 expression as well as NOS and COX signaling pathway activation in murine aortas and mesenteric arteries." (PMID 35784361, 2022). "This indicates that persistent expression of S100A12 by immune cells might not be a bad thing since S100A12 could prevent IL-10 overproduction known to be involved in the immunosuppression in the late stage of sepsis." (PMID 35723375, 2022). "Anti-inflammatory response, including the anti-inflammatory cytokine IL-10, IL-LRA, SIL-LR, STNFR-I and STNFR-II, parallel the overproduction of proinflammatory cytokines, may induce an immunosuppressive state in patients with sepsis." (PMID 36357845, 2022). "Similar results were shown in models of acute lung injury after sepsis (decreased TNF-α, IL-1β, and IL-6 secretion) and paraformaldehyde injury (decreased cell death, MyeloPeroxidase activity, parenchymal vascular permeability, TNF-α and IL-6 secretion, and increased IL-10 secretion)." (PMID 35874678, 2022). "The mice sepsis model is established using lipopolysaccharide (LPS) injection, and the expression levels of proinflammatory cytokines, such as tumor necrosis factor alpha (TNF-α), interleukin-6 (IL-6), and interleukin-10 (IL-10) in both RAW246.7 cells and lung tissues, are tested." (PMID 35814267, 2022). "This supports the hypothesis that the discriminating power of IL-6 and IL-10 for G-/G+ sepsis is independent of the site of infection (bloodstream or non-bloodstream infection)." (PMID 36544765, 2022). "Mice whose NK cells lacked IL-10 (NCR1-CreERT2+/2 Rosa26-tdTomato IL-10flox/flox) had elevated weight loss, increased mortality, and prolonged signs of illness after undergoing CLP20-induced sepsis." (PMID 35053151, 2021). "However, several studies have indicated that a lack of IL-10 leads to better bacterial clearance, a higher survival rate, and limited sepsis-induced immunosuppression." (PMID 34046036, 2021). "No further evidence was provided regarding the role of IL-10-producing NK cells in sepsis." (PMID 35053151, 2021). "The Sepsis + ARDS group had a greater respiratory rate, a lower PaO2/FiO2, a greater SOFA score, and higher levels of lactate (LAC), procalcitonin (PCT), C-reactive protein (CRP), interleukin 6 (IL-6), tumor necrosis factor α (TNFα), IL-10, and FGF21 (all P < 0.05)." (PMID 34154595, 2021). "However, at least in our system, large amounts of IL-10 in early sepsis did not induce immune paralysis." (PMID 33727664, 2021).
Sepsis (continued). "Interestingly, it has been reported that a difference in the IL-10-to-TNF-α ratio was seen in patients with severe sepsis, with nonsurvivors having a ratio of >4.5 48 h after admission." (PMID 34152806, 2021). "Sepsis induction reduced NF-κB and SOD2 protein expression but increased their acetylation, and this was accompanied by an increase in proinflammatory cytokines (TNF-α/IL-6/IL-10) and oxidative stress (indicated by reduced SOD2 activity, GSH content, GSH/GSSG ratio, and CAT activity)." (PMID 33790896, 2021). "We here demonstrate that blood leukocytes of hospitalized CAP patients display an impaired release of TNF-α, IL-1β, IL-6, and IL-10 as well as an heightened production of IL-1RA in response to stimulation with LPS and K. pneumoniae, regardless of the presence of sepsis." (PMID 32477337, 2020). "Elevated ratio of IL-10/TNF-α has been observed in adult sepsis data and suggested to indicate sepsis-induced immunosuppression,; it may therefore indicate relative immunosuppression in preterm infants with sepsis." (PMID 32407417, 2020). "Addition of PTX to GENT in neonatal sepsis, which resulted in significantly diminished TNF-to-IL-10 ratios in cerebral tissue of E. coli-infected mice in our study, might therefore be of particular benefit to protect the vulnerable neonatal brain from sepsis-induced inflammatory injury." (PMID 33072121, 2020). "Similarly, a negative correlation between mHLA-DR and IL-10 plasmatic concentrations was described in burned patients with sepsis." (PMID 33613540, 2020). "Nevertheless, the overexpression of CD155 can significantly increase the production of IL-10 and inhibit the production of IL-12P40 and IL-12P70, suggesting that the expression of CD155 on dendritic cells can promote immunosuppression by regulating the production of cytokines in sepsis." (PMID 32197507, 2020). "Whether or not IL-10 levels correlate with outcome in adult equine patients with naturally occurring sepsis has yet to be investigated." (PMID 30931316, 2019). "Decreased levels of IL-10 and IL-33 indicate that blocking CX43 might improve the long-term outcomes, as these cytokines have been shown to be involved in immunosuppression following sepsis." (PMID 30735126, 2019). "Biomarkers of inflammation and sepsis investigated in foals and adult horses include lactate, soluble CD14 (sCD14), serum amyloid A, procalcitonin, C-reactive protein (CRP), haptoglobin (Hp), interleukin 1β (IL-1β), interleukin-10 (IL-10), and interleukin-6 (IL-6)." (PMID 30931316, 2019). "Moreover, we have shown that mice fed with omega-9 and submitted to sepsis produced less proinflammatory cytokines and more IL-10, which agrees with studies showing the activation of PPAR gamma-enhanced production of the anti-inflammatory cytokine IL-10." (PMID 30538802, 2018). "We also demonstrated that the levels of GM-CSF in B-1a cells between WT and IL-10−/− mice strains following sepsis were remained same, indicating that the lack of IL-10 in B-1a cells could be detrimental in sepsis without affecting the levels of GM-CSF." (PMID 30134811, 2018). "However, the IL-10 rate of change was not calculated as IL-10 is a pre - inflammatory biomarker, and is used to diagnose sepsis rather than survival prognosis in sepsis patients." (PMID 30400775, 2018). "Since B-1a cells are known to produce excessive amounts of anti-inflammatory cytokine IL-10, it is therefore understandable that the B-1a cells could temper the pro-inflammatory responses of alveolar macrophages and thus protect mice from ALI during sepsis." (PMID 30134811, 2018). "However, the relationship between IL-10/lymphocyte ratio(IL10LCR) and the mortality of severe sepsis patients remains unknown." (PMID 28628675, 2017).
Sepsis (continued). "Peripheral blood from sepsis survivors was collected 5–10 months after sepsis diagnosis and analysed for the frequency, and the absolute number of CD4+Foxp3+ T cells and serum concentration of IL-33 and IL-10 together with age- and sex-matched healthy volunteer blood donors (n=14)." (PMID 28374774, 2017). "The AUCs for IL-2, IL-6, IL-10 and CRP were 0.901 (95% CI, 0.866 to 0.930), 0.86 (95% CI, 0.821 to 0.894), 0.888 (95% CI, 0.851 to 0.918) and 0.848 (95% CI, 0.807 to 0.883) respectively, indicating that IL-2, IL-6 and IL-10 were effective biomarkers to rule out sepsis and intracranial infection." (PMID 24887408, 2014). "In a murine model of sepsis, the high affinity orthosteric agonist, ATL313, decreases circulating plasma levels of pro-inflammatory cytokines and chemokines such as TNF-α, MIP-1α, MCP-1 and increases the plasma level of the anti-inflammatory cytokine IL-10 within 4 h of LPS injection." (PMID 25473378, 2014). "The AUCs for IL-2, IL-6 and IL-10 were 0.901 (95% CI, 0.866 to 0.930), 0.860 (95% CI, 0.821 to 0.894), 0.888 (95% CI, 0.851 to 0.918), respectively, indicating that IL-2, IL-6 and IL-10 were effective biomarkers to rule out sepsis and intracranial infection." (PMID 24887408, 2014). "When examining the inflammation and immune related signaling pathways in IPA, we found that the Il-10 signaling pathway was more significantly expressed after CLP than CS across all three time points and had the greatest proportion of up-regulated genes two hours after sepsis." (PMID 24788351, 2014). "Interestingly, increase of TNF-α and IL-1β concentrations, but not IL-10 in plasma after administration of nociceptin has been also reported in a rat model with sepsis." (PMID 24066107, 2013). "Results of our study afforded scientific evidence for BHT in treating sepsis by a CLP model and its effects on cytokine modulation: early administration of high-dose BHT markedly improved survival by directly reducing plasma level of IL-6, and simultaneously decreased IL-10 was observed." (PMID 23762108, 2013). "Furthermore, we found that NOD2-mediated IL-10 production by neutrophils enhanced C5a generation by suppressing CD55 expression on neutrophils in IL-1β-dependent and/or IL-1β-independent manners, thereby aggravating CLP-induced sepsis." (PMID 23675299, 2013). "Lymphocyte subpopulations differentially undergo apoptosis during sepsis with a high resistance within the CD25+ subset: in this context it is therefore likely that these cells may give their suppressive contribution through the release of sCD25 and IL-10." (PMID 23561467, 2013). "We also looked at the IL-10 value in patients with sepsis and patients without sepsis." (PMID 22529517, 2012). "MCP-1 positively regulates IL-10 but negatively controls macrophage migration inhibitory factor (MIF) in experimental peritoneal sepsis, suggesting an important immunomodulatory role for MCP-1 in controlling the balance between proinflammatory and anti-inflammatory factors in sepsis." (PMID 22272381, 2012). "IL-10 is known to attenuate the synthesis of TNF-α surface receptor and its suppressive effects may be beneficial in pathology that results from inflammatory dysregulation such as in sepsis." (PMID 22035174, 2011). "Nonetheless, there appeared to be differences in the pattern of cytokine concentrations related both to the presence or absence of sepsis and to the nutritional management of the animals, with recovery of circulating IL-6 and IL-10 being more frequent in animals with sepsis administered PN." (PMID 17634149, 2007). "Furthermore, in a mouse model of sepsis, the SIRT1 activator resveratrol can alleviate inflammatory responses and organ damage by upregulating IL-10 expression, suggesting that SIRT1-induced IL-10 can significantly antagonize the inflammatorycascade amplification mediated by NF-κB." (PMID 38745862, 2024).